IL9 (interleukin 9)
Diseases named in the same sentence as IL9 in open-access papers (continued):
Sharing a sentence is not in itself a finding about the gene and the disease.
asthma (continued). "In vivo, several inflammatory conditions induce IL-9, including asthma, atopic and contact dermatitis, food allergies and bacterial infections." (PMID 41030439, 2025). "In an asthma exacerbation model induced by poly I:C, the reduction of inflammatory mediators such as IL-13 and IL-9 can significantly alleviate airway inflammation and hyperresponsiveness." (PMID 40636260, 2025). "Th9 cells, through IL-9 production, play a role in various immune-related diseases, including tumors, inflammatory diseases, parasite infections, and asthma." (PMID 40072125, 2025). "Tc2 levels, particularly IL‐5+ and IL‐9+ Tc cells, peaked during asthma exacerbations at ~25% of circulating Tc cells, rivalling the quantitative increases observed for Th cells." (PMID 40016948, 2025). "In recent studies using IL-9 transgenic mice, in vivo expression of IL-9 was found to lead to increased airway hyperresponsiveness, mimicking features observed in human asthma." (PMID 38337546, 2024). "IL-9 plays a pivotal role in the pathogenesis of asthma by promoting eosinophil activation and enhancing IgG/IgE production by B cells." (PMID 38483511, 2024). "In contrast, asthma can increase levels of IL-5 [odds ratio (OR) = 1.112, 95% confidence interval (CI): 1.009–1.224, P = 0.032] and IL-9 (OR = 1.111, 95% CI: 1.013–1.219, P = 0.025)." (PMID 39175819, 2024). "The contribution of Th9 cells, a distinctive subset of T-cells that produce IL-9, to asthma pathogenesis remains debatable as there is a paucity of research studies covering this topic." (PMID 39060923, 2024). "IL-9 promotes the pathogenesis of asthma by activating and recruiting mast cells and eosinophils, enhancing B-cell IgE production, increasing epithelial cell mucus production, and triggering airway AHR." (PMID 37377958, 2023). "The expression of Id1 as well as Il9 was significantly increased in CD4 T cells from the asthma‐induced mice, highlighting the physiological significance of Id1." (PMID 37867222, 2023). "IL-9 has been studied in great depth in the T cell mediated immune response in various pathological conditions ranging from asthma, autoimmunity to cancer." (PMID 36732282, 2023). "Upon exacerbating, asthma patients showed significantly decreased frequencies of IFNγ+ and simultaneously increased frequencies of IL-4+, IL-5+, and IL-9+ Tc and Th cells." (PMID 37612281, 2023). "The induction of DUSP8 and IL-9 in the same T cells of people with asthma were also detected by immunofluorescence staining." (PMID 37909329, 2023). "Whereas total Tc/Th cell frequencies were similar between asthma patients and HCs, production of the type-2 cytokines IL-5, IL-9, and IL-13 by both Tc and Th cells was significantly higher in asthma patients than in HCs." (PMID 37612281, 2023). "Here we provide compelling evidence that the Tc cell compartment in asthma undergoes substantial phenotypic skewing, resulting in a functional shift away from type-1 (e.g., IFNγ) and towards type-2 (e.g., IL-5, IL-9) cytokine production." (PMID 37612281, 2023). "Some other Th cell subsets such as Th9 and Th22 have been described by some laboratories as being involved in the secretion of IL-9 and IL-22, respectively, which are associated with airway inflammation and AHR in asthma." (PMID 37377958, 2023). "Despite of the induction of mucus and Th2 cytokines in OVA-induced acute allergic asthma model, IL-9 slightly affects the cellular changes in asthma." (PMID 35524325, 2022). "Among them, Th2 cells play a major role in asthma pathogenesis by secreting various cytokines such as IL-4, IL-5, IL-9, and IL-13, while IFN-γ secreted by Th1 inhibits Th2 function." (PMID 35815290, 2022). "In a study of allergic asthma, it was observed that IL-9 participates in the pathogenesis and development of asthma." (PMID 36172190, 2022). "Meanwhile, the Flow cytometry results revealed the higher proportion of CD4+T cells secreting IL-9 in the PBMCsof the asthma mice." (PMID 36253857, 2022).
asthma (continued). "Th9 cells and IL-9 promote accumulation and activation of T cells, ILC2s, mast cells, and eosinophils and increase levels of IL-5, IL-13, and IgE in animal asthma models." (PMID 35807067, 2022). "The role of interferon (IFN)-γ in asthma has been debated because, like IL-9, this has pleiotropic roles in influencing the properties and functions of target cells." (PMID 36304255, 2022). "In murine models of asthma, IL-9 has shown a role in driving AHR, airway remodeling, mast cell survival, and mucous cell metaplasia." (PMID 36032162, 2022). "Th2 cells secrete IL-4, IL-5, IL-9, IL-13 and other inflammatory factors, among which IL-4 and IL-13 are the regulators of asthma." (PMID 35744915, 2022). "In asthma, IL-9 appears to promote the proliferation of activated T cells and production of IgE by B cells." (PMID 36304255, 2022). "Asthma patients have increased numbers of Th9 cells in peripheral blood mononuclear cells (PBMCs) and increased IL-9 levels in both serum and bronchoalveolar lavage fluid (BALF)." (PMID 35807067, 2022). "Th9 cells produce the cytokines IL-9, IL-10, and IL-21; however, IL-9 is likely to contribute to asthma pathology." (PMID 36078171, 2022). "The cytokines secreted by Th2 cells are mainly IL-4, IL-5, IL-13, and IL-9 which have different roles in the pathogenesis of asthma." (PMID 36032162, 2022). "Serum IL-4, IL-9, and IL-13 levels were significantly (p < 0.01) enhanced in the asthma group compared with the control group." (PMID 33577738, 2021). "Increased serum levels of IL-8, as well IL-4, IL-5, and IL-9 have been reported in asthma hyperreactivity following Th2 lymphocyte release." (PMID 34884340, 2021). "In murine models IL-9 seems to be critical for the induction of allergic airway inflammation, as the administration of blocking antibodies reduced asthma features." (PMID 34868033, 2021). "Mouse models of asthma showed increased numbers of IL-9 expressing infiltrating T cells in the lungs when exposed to allergens including house dust mites (HDM), aspergillus, ovalbumin (OVA), and papain." (PMID 33748292, 2021). "Another study revealed that IL-9 rs1859430 genotype frequencies were lower in asthma patients than in controls under the recessive GA+AA (p = 0.021) and heterozygous GA (p = 0.031) models." (PMID 33953642, 2021). "Although ILC2s are thought to induce inflammation in patients with asthma, researchers found that they also protect against inflammation by releasing IL-9." (PMID 34177881, 2021). "Mapping studies in mice and humans have shown that IL-9 is an asthma-related gene, and anti-IL-9 antibodies have been trialed to treat asthma patients in a clinical setting." (PMID 32258172, 2020). "Th9 is a novel Th cell subset that mainly produces IL-9, a potent proinflammatory cytokine in asthma." (PMID 32258172, 2020). "Increased sensitivity to STAT5 activation was further correlated with increased IL9 locus accessibility in cells from patients with a diagnosis of asthma." (PMID 32985505, 2020). "Recently, the anti-IL-9 antibody has been used to treat asthma patients in the clinical trial (phase II) at the NIH." (PMID 32258172, 2020). "IL-9 and IL-2 work synergistically to direct ILC2 biology, and increased IL-9 production is related to an asthma-like phenotype in humans and mice highlighting the key role of these cytokines." (PMID 33193374, 2020). "It is well recognized that asthma is an immune response driven by Th2 and Th17 cells with cytokines such as IL-4, IL-5, IL-9, IL-10, IL-13, and IL-7 playing important roles." (PMID 33123005, 2020). "Interleukin (IL)-9 is a pro-inflammatory Th2 cytokine with a pivotal role in asthma, allergy and chronic obstructive pulmonary disease (COPD), but is less studied in CRSwNP." (PMID 33292477, 2020). "Th9 responses mediated by IL-9 secretion have been reported to participate in tissue inflammation and immune-mediated diseases ranging from autoimmunity to asthma." (PMID 33375675, 2020).
asthma (continued). "Th9 cells secrete IL-9, IL-10, and other cytokines, which play essential roles in human asthma pathogenesis." (PMID 32258172, 2020). "Consistently, pulmonary overexpression of IL-9 was found to enhance immunopathology in allergic inflammation in asthma in mice." (PMID 31164892, 2019). "IL-9 and IL-9-producing cells play a role in helminth infections, allergic diseases (such as asthma), autoimmunity, and tumor suppression." (PMID 32082072, 2019). "Similar histopathological changes which are characteristics of human asthma are induced in animals after lung instillation of recombinant IL-9 (rIL-9) for ten days." (PMID 31035677, 2019). "Group 2 consists of the anti-IL-4Rα antibody, anti-IL-5 antibody, anti-IL-13 antibody, anti-IL-9 antibody, and anti-IL-17 antibody, which are the investigational drugs for asthma." (PMID 31284537, 2019). "Promising results in animal studies have directed two randomized placebo-controlled studies to assess the safety profile and potential efficacy of different doses of MEDI-528, a humanized anti-IL-9 monoclonal antibody, in asthma patients." (PMID 31035677, 2019). "The anti-IL-9 antibody inhibited the pulmonary infiltration of inflammatory cells and decreased the production of cytokines IL-5, IL-9, and IL-17 in murine asthma models." (PMID 31284537, 2019). "Patients suffering from asthma have higher levels of IL-9 producing T-cells in their peripheral blood." (PMID 32010048, 2019). "Consistently, subsequent studies have shown that neutralization of IL-9 with anti-IL-9 antibody reduced the allergic inflammation in animal model of asthma, suggesting an important role of IL-9 in disease pathogenesis." (PMID 31164892, 2019). "There is evidence suggesting that IL-9 production in Th17 cells has been related to autoimmune disease including type 1 diabetes, asthma, and experimental autoimmune encephalomyelitis." (PMID 32116681, 2019). "Interleukin-9 (IL-9) is a pleiotropic cytokine and was primarily studied in the context of T helper 2 (TH2)-associated immuno-pathological conditions such as asthma and parasitic infections." (PMID 31035677, 2019). "It was demonstrated that NO enhances differentiation of Th9 cell, and therefore exacerbates IL-9, and Th9 dependent allergic inflammation in asthma." (PMID 30692989, 2018). "As important Th2 cytokines, interleukin (IL)-9 and eotaxin are reported to be involved in the development of asthma, and are supposed to be useful in the diagnosis and assessment of asthma." (PMID 29769601, 2018). "Since asthma is contributed by waves of different cytokines such as IL-4, IL-5, IL-13, and IL-9, hence it is needful to define and identify the predominant cytokine signature and subtype that is inducing the disease." (PMID 29867972, 2018). "This was in agreement with other findings which identified that lung-expression of IL-9 increased IgE-mediated disease pathology and mucus production in mouse model of asthma." (PMID 29867972, 2018). "We also determined the levels of IL-9 and eotaxin, which were considered to be helpful in the diagnosis of asthma." (PMID 29769601, 2018). "On this regard, MEDI−528, a humanized mAb against IL-9, is already used in clinics for the treatment of asthma." (PMID 30515173, 2018). "We found that the average levels of IL-9 in asthma cases (71.79 ± 7.45 pg/ml) were significantly higher than that in controls (35.47 ± 6.70 pg/ml)." (PMID 29769601, 2018). "FA aggravates asthma, at least in part by increasing the T helper-2 dominant response, which is related to levels of the cytokine mediators of asthma (IL-4, IL-5, IL-9, and IL-13)." (PMID 29780828, 2018). "Corroborating in vitro data, in vivo blockade of Foxo1 resulted in reduced signs of asthma as measured by AHR and associated with reduced frequency of IL-9+CD4+T cells in the lungs." (PMID 29867972, 2018).
asthma (continued). "The expression of IL-9 in asthma cases was significant higher than that in controls, but the expression of eotaxin was significant higher in controls when compared with cases." (PMID 29769601, 2018). "The adjusted ORs (95%CI) of association between IL-17A, IL-9, adipsin and CCL11 expressions and adult asthma were 3.08 (1.91, 4.97), 1.93 (1.41, 2.64), 10.02 (6.99, 14.37) and 3.29 (2.36, 4.59), respectively (all Ptrend < 0.0001)." (PMID 29138487, 2017). "This gene set includes numerous cytokines that mediate Th2 cell signaling associated with asthma (IL3, IL4, IL5, IL9, IL10 and IL13), as well as components of the IgE receptor (FCERA, FCERG, MS4A2) and eosinophil granule proteins (ECP, EDN, EPX, and MBP)." (PMID 28854632, 2017). "In conclusion, we found that elevated plasma IL-17A and IL-9 levels and decreased plasma expressions of adipsin and CCL11 were positively associated with asthma risk in adults." (PMID 29138487, 2017). "Our data demonstrated therapeutic efficacy of Foxo1-siRNA and Foxo1 inhibitor in inhibiting IL-9 and ameliorating signs of ova-induced asthma in mice." (PMID 28993609, 2017). "Our results suggested that elevated IL-17A and IL-9 expressions and decreased levels of adipsin and CCL11 were positively associated with adult asthma." (PMID 29138487, 2017). "IL-9 immunoreactivity was found to a less magnitude in the epithelium, endothelium, and mucus glands in patients with severe asthma with CRS." (PMID 28199345, 2017). "The Th2-derived cytokines, IL-4, IL-5, IL-9, and IL-13 mRNA expression was also markedly increased in the patients with severe asthma patients with CRS." (PMID 28199345, 2017). "In this study, we observed that the plasma levels of IL-17A and IL-9 were significantly increased in asthma cases when compared with controls." (PMID 29138487, 2017). "Inhibition of Foxo1 not only suppressed IL-9 induction IL-9-producing T cells but also ameliorated development of asthma." (PMID 28993609, 2017). "The targets of IL-9 include mast cells, T-cell clones, and B-lymphocytes, through which IL-9 plays a crucial role in immune reactions against parasites, asthma, and lymphoma development." (PMID 28349057, 2017). "Th9 cells, which mainly produce IL-9 form another T cell subset that has recently been described to drive asthma development." (PMID 27468754, 2016). "In human adult patients with mild to moderate asthma, treatment with anti-IL-9 MEDI-528 showed first promising results." (PMID 27468754, 2016). "Mouse models of asthma have highlighted the role of IL-9, as treatment of asthmatic mice with neutralizing antibodies to IL-9 significantly alleviates symptoms." (PMID 26346739, 2015). "IL-9 has also been recently evaluated for its use as an asthma biomarker given its heightened expression in the lungs of asthmatic patients." (PMID 26346739, 2015). "Th2 cells, which are characterized by IL-4, IL-5, IL-9 and IL-13 cytokine production, predominate in asthma, whereas Th1 cells producing IFN-γ, IL-2 and TNF have rarely been associated with asthma." (PMID 25132806, 2014). "IL-9+ T cells act proinflammatory and are involved in immune mediated diseases ranging from autoimmunity to asthma." (PMID 24692846, 2014). "The aim of this study was therefore to evaluate the effects of MEDI-528, an anti-interleukin-9 monoclonal antibody, in adults with confirmed uncontrolled moderate-to-severe asthma." (PMID 24050312, 2013). "Despite convincing in vitro and animal model data, there have been very few studies in humans examining IL-9 involvement in asthma." (PMID 24050312, 2013). "Preclinical studies in animal models of asthma support a contributing role for an IL-9 mast cell axis in the immunopathology of asthma." (PMID 24050312, 2013).
asthma (continued). "Data from preclinical studies provide strong evidence that an IL-9 mast cell axis regulates airway inflammation, mucus production, airway hyperresponsiveness, and subepithelial fibrosis, with increased IL-9 expression in the airways in humans with asthma." (PMID 24050312, 2013). "While cytokine selective therapeutic strategies have proven to be problematic in most studies, ongoing Phase II studies of the impact of blocking IL-9 function are underway in asthma." (PMID 23071516, 2012). "Evidence supporting IL-9 as a potential target treatment for asthma emerged from a series of genetic experiments linking AHR to a region on chromosome 13 in mice, which contains the IL-9 gene and is syntenic with the 5q31-q33 chromosome in humans." (PMID 21356110, 2011). "For example, IL-9 had been shown to participate in the defense against helminth infections, asthma and allergy." (PMID 21635745, 2011). "Various cell types involved in allergy and asthma are known to express the IL-9 receptor, however the physiological role of IL-9 is currently not well understood." (PMID 21765905, 2011). "A recent paper suggests that while IL-9 plays only a marginal role in modulating the inflammation in an acute asthma model, there seems to be a more profound effect in a model of chronic asthma with repeated allergen challenges." (PMID 21765905, 2011). "Blocking IL-9 expression inhibits airway inflammation in a mast cell-dependent murine model of asthma." (PMID 21356110, 2011). "Th2 cytokines also activate secondary effector cells in asthma including the recruitment of mast cells (IL-4, IL-9 and IL-13) and basophils (IL-3 and IL-4), whilst IL-5 supports growth, differentiation, and activation of eosinophils." (PMID 19769993, 2010). "Numerous in vitro and in vivo studies in both animals and patients with asthma have shown that IL-9 is an important inflammatory mediator in asthma." (PMID 18315837, 2008). "Interleukin (IL)-9 is a Th2-derived cytokine with pleiotropic biological effects, which recently has been proposed as a candidate gene for asthma and allergy." (PMID 15823208, 2005). "The increased expression of IL-4, IL-9, and IL-13 in our non-T2 children may appear paradoxical but likely reflects that children with severe asthma have elevated ILC2s even when they are non-T2 (low eosinophils)." (PMID 41601686, 2026). "However, in the same IL-9-overexpressing transgenic mouse strain, IL-9 played a profibrotic role in airway remodeling in a model of asthma." (PMID 41465219, 2025). "Notably, patients with mild asthma who were treated with a humanized anti-IL-9 monoclonal antibody (MEDI-528) reported fewer asthma exacerbations and reduced post-exercise FEV1 decline than patients treated with a placebo." (PMID 40771819, 2025). "In patients with recurrent wheezing induced by RSV and HRV, the expression level of IL-9 are higher.Virus-induced asthma attacks are characterized by an increase in Th1-type neutrophils and Th2-type inflammation, which is associated with the secretion of IL-1β." (PMID 40636260, 2025). "Despite the central role of Th2 cells in producing type 2 cytokines, the field has kept a keen interest in identifying other sources of IL‐4, IL‐5, IL‐9, and IL‐13, which may also be relevant for asthma pathobiology." (PMID 40016948, 2025). "Similarly, Waldman and Robinson meta-analysis of linkage studies between asthma and the IL-9 gene showed that the IL-9 gene has little correlation with the pathogenesis of asthma." (PMID 39175819, 2024). "IL-9 increases airway sensitivity, a characteristic feature of asthma." (PMID 39407835, 2024). "Finally, in asthma animal models, IL-9 regulates airway inflammation, mucus production, airway hyperresponsiveness, and airway fibrosis." (PMID 38337546, 2024). "Repression of IL‐9 synthesis can be accomplished by utilizing a secretory substance derived from parasites, thus providing potential safeguard against experimentally induced asthma." (PMID 38888451, 2024).